SMIM45 (small integral membrane protein 45)
Description:
Plays a role in the regulation of neuron maturation.
Synonyms: LINC00634; BK250D10.8
Gene: Protein-coding gene on chromosome 22 (41,947,178 to 41,958,942, forward strand). Ensembl gene ENSG00000205704.
Subcellular location: Nucleus; Cytoplasm; Membrane
Gene Ontology:
Biological process: neuron maturation
Cellular component: cytoplasm; nucleus; membrane
Homologues: Orthologues: chimpanzee SMIM45 (100% identical), rabbit SMIM45 (100% identical), rat Smim45 (100% identical), guinea pig SMIM45 (99% identical), mouse Smim45 (99% identical), pig SMIM45 (97% identical).
Diseases named in the same sentence as SMIM45 in open-access papers:
SMIM45 is named in the same sentence as 7 diseases in open-access papers, as found by Europe PMC text mining. Sharing a sentence is not in itself a finding about the gene and the disease. The quoted sentences say what the papers report.
tumor (3 papers, 2021 to 2023). "Recently, our group reported the increased expression of LINC00518 (long intergenic non-protein coding RNA 518) and LINC00634, now named SMIM45 (small integral membrane protein 45), in a cohort of forty-one UM patients comparing tumor and normal adjacent tissues." (PMID 36765733, 2023).
SMIM45 also shares sentences with these, for which no sentence is quoted: esophageal squamous cell carcinoma (2 papers); breast carcinoma (1); cervical cancer (1); esophageal cancer (1); gastric cancer (1); glioma (1).